POLG (DNA polymerase gamma, catalytic subunit)
Diseases named in the same sentence as POLG in open-access papers (continued):
Sharing a sentence is not in itself a finding about the gene and the disease.
liver failure (21 papers, 2011 to 2025). A liver disease characterized by the liver losing or has lost all of its function. "Valproic acid exacerbates liver failure in the presence of a POLG mutation, and one should refrain from using it unless a POLG mutation is excluded." (PMID 39184802, 2024). "Polymerase subunit gamma (POLG) is a mitochondrial gene, and an infant POLG mutation can manifest with severe and progressive hepatic failure and encephalopathy, imposing a difficult differential diagnosis due to similarities to other conditions." (PMID 39184802, 2024). "Questions remain unsolved regarding the link between genetic findings and prognosis, not only related to survival, but also to hepatic failure in the presence of valproate, which should be avoided in carriers of POLG genetic variants." (PMID 33113942, 2020). "Valproate can precipitate liver failure in Alpers disease, and this was documented in POLG-mutated adolescent and early-adulthood patients treated with valproate for status epilepticus." (PMID 33113942, 2020). "Other defects of POLG are associated with valproate induced liver failure, further in support that mtDNA replication is essential for optimal hepatocyte function." (PMID 27053192, 2016). "It has been shown that VPA should not to be used to treat patients with mitochondrial disease, particularly because patients with POLG mutations are at increased risk for VPA-induced liver failure." (PMID 23448099, 2013). "This is very important for clinical diagnostics, genetic counseling, and treatment decisions because of the increased risk for VPA-induced liver failure in patients with POLG mutations." (PMID 23448099, 2013). "Recent studies gave evidence that POLG mutations can lead to a range of clinical phenotypes which predispose to the development of fatal liver failure after exposure to VPA." (PMID 21235791, 2011). "From a clinical perspective, patients with pathogenic variants in the POLG-gene affecting mitochondrial health may present a wide range of clinical symptoms, ranging from mild muscle weakness to stroke-like episodes and liver failure." (PMID 40004527, 2025). "The authors interpreted that these postmortem findings were compatible with severe liver impairment, and hypothesized that KD can potentially progress liver failure in patients with pathogenic POLG variants." (PMID 36142570, 2022). "However, it is important to avoid certain drugs with known mitochondrial toxicity, such as sodium valproate, in patients with POLG mutations (due to the risk of hepatic failure and seizure aggravation)." (PMID 36362003, 2022). "Since the initial description of liver failure following VPA treatment in AHS patients carrying POLG mutations numerous, similar cases have been described, leading to a statement recommending the avoidance of valproic acid in children with a suspected POLG-related disease." (PMID 24725338, 2014). "Furthermore, recent studies in this area reinforced, in particular, evidence that certain mutations in POLG can lead to a range of clinical phenotypes which predispose to development of fatal liver failure after exposure to valproic acid (VPA)." (PMID 21235791, 2011). "Genetic forms of mtDNA depletion are associated with a predominant hepatopathy, however, other organs (including muscle and brain) may also be involved, such as in epileptic encephalopathy, liver failure and visual impairment in Alpers-Huttenlocher syndrome due to autosomal recessive POLG mutations." (PMID 27053192, 2016). "In AHS, liver impairment and acceleration to severe liver failure are part of the disease pathogenesis due to the dysfunction of POLG." (PMID 36142570, 2022). "The infantile phenotypes of hepatocerebral forms of MDS associated with mutations in POLG, PEO1 (Twinkle), DGUOK or MPV17 have similarities, presenting with liver failure along with various neurological and endocrinological manifestations." (PMID 23714749, 2014).
liver failure (continued). "The continuous lack of response to treatment might suggest a non-reversible etiology of hepatic failure, like a POLG mutation." (PMID 39184802, 2024). "This raises the possibility that genetic variation in POLG may predispose individuals to VPA-induced liver failure who may not have a recognizable phenotype like AHS." (PMID 24725338, 2014). "This study emphasizes that genetic testing for POLG mutations in patients with nonsyndromic intractable epilepsies is very important for clinical diagnostics, genetic counseling, and treatment decisions because of the increased risk for VPA-induced liver failure in patients with POLG mutations." (PMID 23448099, 2013). "A recent review described four POLG patients (age range 3 to 18 years) given VPA for intractable partial seizures followed by liver failure where the time from VPA exposure to liver failure was 2–3 months, posing the question of whether POLG sequencing should be considered prior to VPA treatment." (PMID 23448099, 2013). "Sequencing of the DGUOK, POLG and MPV17 genes did not reveal the causative mutation, however, it is possible that the mtDNA depletion contributed to the liver failure in these patients." (PMID 27053192, 2016). "Based on the VPA-induced liver failure in patients with POLG-related disease, we expected a negative effect of VPA on the expression of POLG and other mitochondrial genes." (PMID 24725338, 2014).
External ophthalmoplegia (19 papers, 2013 to 2025). Paralysis of the external ocular muscles. "The three newly solved cases included one patient with a typical autosomal recessive RYR1-associated myopathy, and a patient with chronic progressive external ophthalmoplegia and late-onset parkinsonism who had a likely pathogenic POLG variant." (PMID 38127101, 2024). "The other group had chronic progressive external ophthalmoplegia (CPEO) associated with variants in the POLG gene, which encodes the DNA Polymerase Gamma, Catalytic Subunit (POLG) that is responsible for replicating mtDNA." (PMID 40034369, 2024). "The disorder has also been misdiagnosed as other mitochondrial DNA depletion syndromes such as POLG or RRM2B mutations or other mitochondrial diseases, including Kearns-Sayre syndrome and chronic progressive external ophthalmoplegia." (PMID 32914088, 2020). "Mutations in POLG, which lead to the accumulation of multiple mtDNA deletions over time, have been associated with Alpers-Huttenlocher syndrome (AHS) in children and chronic progressive external ophthalmoplegia (CPEO) in adults." (PMID 35513611, 2022).
MELAS (18 papers, 2009 to 2025). "Focal onset status epilepticus was identified in almost all stroke-like episodes in patients with POLG variants compared to about a fifth of mtDNA-related MELAS syndrome [27/28 (96%) versus 19/87 (22%), P = 0.007]." (PMID 34927673, 2022). "Of the 34 patients with a genetic diagnosis of mitochondrial diseases, 44.1% (n = 15) were diagnosed with MELAS, 26.5% (n = 9) with Coenzyme Q10 deficiency, 11.8% (n = 4) with Leigh syndrome and 8.8% (n = 3) with POLG mutation." (PMID 41438888, 2025). "In this study, stroke-like episodes in genetically defined mitochondrial disorders were most frequently observed in MELAS and POLG mutations, and rarely in CoQ10 deficiency, Leigh syndrome cases." (PMID 41438888, 2025). "Seizures are particularly common in mitochondrial disorders such as polymerase gamma (POLG) mutations, mitochondrial encephalomyopathy, lactic acidosis, and stroke-like episodes (MELAS), and myoclonic epilepsy with ragged-red fibers (MERRF)." (PMID 34912288, 2021). "Of note, the m.13565C>T MT-ND5 mutation studied here was originally isolated from a MELAS patient who also carries a mutation in POLG, which encodes the catalytic subunit of the mitochondrial DNA polymerase." (PMID 27110715, 2016). "The most common cause of MELAS phenotype is m.3243A>G mutation which accounts for 80 % of cases but mutations in the nuclear gene POLG, encoding for the catalytic subunit of DNA polymerase γ (pol γ), can cause similar stroke-like lesions." (PMID 26315846, 2016). "The second cluster consisted of all patients harboring isolated complex IV deficiency, three patients with isolated complex I deficiency (TIMMDC1 and mt-ND3), one patient with complex V deficiency, one MELAS patient, and one patient with DNA polymerase subunit gamma (POLG) deficiency." (PMID 39801833, 2025). "POLG variants have also previously been associated with MELAS and MELAS-like phenotypes." (PMID 35699875, 2022). "Similarly, ubiquinone deficiencies, MELAS, POLG (polymerase subunit gamma) mutation, and Kearns-Sayre Syndrome are all associated with various lesions and brain MRI abnormalities, including alterations in the cerebral cortex, seizure, or stroke-like episodes." (PMID 31139141, 2019). "Status epilepticus in MD is more common in patients with damage to mtDNA (especially in MELAS and MERRF syndromes) and mitochondrial depletion syndromes (especially with pathogenic changes in POLG) and are co-existent with stroke-like episodes." (PMID 34206602, 2021). "Of the 13 patients with SLE, 46.1% (n = 6) were diagnosed with MELAS and 23.1% (n = 3) with POLG." (PMID 41438888, 2025). "While stroke-like episodes are classic of MELAS, they occurred in two patients with multisystem disease and one patient with SANDO, all with pathogenic variants in POLG (c.1399G>A in homozygosity in two patients and c.1491G>C in compound heterozygosity with c.2243G>C in another)." (PMID 38434220, 2024). "It is tempting to speculate that a more marked loss of brain weight in patients with mtDNA variants reflects their typically insidious onset and protracted course of disease, while patients with POLG-related MELAS have an explosive onset and rapid progression." (PMID 34927673, 2022). "Our case had some atypical aspects for MELAS such as late onset, lack of cerebral calcification and presence of frontal and occipital MRI lesions better consistent with the POLG associated-encephalopathy spectrum." (PMID 23324391, 2013). "Patients who present with classic syndromes such as MELAS, MERRF, LHON and Alpers disease can be diagnosed by direct sequencing of mitochondrial genes or POLG gene in blood." (PMID 26315846, 2016).
neuropathy (18 papers, 2012 to 2025). A disorder affecting the nervous system that manifests with pain, tingling, numbness, and/or muscle weakness. "Neuropathy in the context of mitochondrial disease is thought to be more associated with specific nuclear gene defects, in particular POLG mutations." (PMID 32334903, 2020). "Low penetrance of pathologies such as migraines and neuropathies was suggested for simple heterozygous carriers of strongly pathogenic POLG variants." (PMID 26077851, 2015).
Stroke (14 papers, 2013 to 2026). Sudden impairment of blood flow to a part of the brain due to occlusion or rupture of an artery to the brain. "In this report, we describe the case of a 19-year-old female patient with two heterozygous POLG variants in different exons manifesting phenotypically as polyneuropathy and later with a first stroke-like episode (SLE) and seizures." (PMID 40062103, 2025). "The stroke-like lesions in POLG variants are commonly located in posterior brain regions, especially in the occipital lobe, but also thalamic lesions have been reported." (PMID 39666093, 2024). "Stroke‐like episodes were also common and featured in six patients of which four patients harboured the m.3243A>G mutation, one patient harboured the m.8344A>G mutation (patient 6) and one harboured autosomal recessive mutations in POLG (patient 8)." (PMID 25786813, 2016). "Broadening this question beyond LHON would allow researchers to look at the broad phenotypic expression seen in POLG‐associated mitochondrial disease, and particularly those people in teenage years who may present de novo with seizures or stroke‐like episodes and whether there is a sex effect here." (PMID 35543492, 2022). "POLG variants are known to cause stroke-like episodes and the features in SLE seem to be similar in patients with mtDNA and POLG variants." (PMID 39666093, 2024). "The mean onset age of POLG-related seizures and stroke-like episodes has been reported to be 17–18 years, which is significantly lower than patients with mtDNA variants." (PMID 39666093, 2024). "The most common genetic cause of stroke-like episodes was the m.3243A>G variant in MT-TL1 (n = 66), followed by recessive pathogenic POLG variants (n = 22), and 11 other rarer pathogenic mitochondrial DNA variants (n = 23)." (PMID 34927673, 2022). "Patients with POLG-related stroke-like episodes demonstrated more fulminant disease trajectories than cases of m.3243A>G and other mitochondrial DNA pathogenic variants, in terms of the frequency of refractory status epilepticus, rapidity of progression and overall mortality." (PMID 34927673, 2022). "Moreover, stroke-like episodes were a significant predictor of early death in both m.3243A>G (HR 12.3, 95% CI 5.8–26.5, P < 0.001) and POLG (HR 11.6, 95% CI 4.7–28.2, P < 0.001) patients." (PMID 34927673, 2022). "Interestingly, we found no stroke‐like events in the patients with the POLG mutation." (PMID 26381753, 2015).
mitochondrial DNA depletion syndrome (13 papers, 2012 to 2025). The mitochondrial DNA (mtDNA) depletion syndrome (MDS) is a clinically heterogeneous group of mitochondrial disorders characterized by a reduction of the mtDNA copy number in affected tissues without mutations or rearrangements in the mtDNA. "Fifty percent of patients were diagnosed with genetic syndromes, 37.5% of them with mitochondrial DNA depletion syndrome with POLG mutations, a severe degenerative neurological disease with per se unfavorable outcome." (PMID 34149600, 2021). "Mutations in POLG can cause early childhood mtDNA depletion syndromes or later-onset syndromes resulting from mtDNA deletions." (PMID 32566083, 2020). "Hypergonadotropic hypogonadism has also been reported in patients with mitochondrial diseases, including mtDNA depletion syndromes (C10orf2, POLG variants), mitochondrial neurogastrointestinal encephalomyopathy (MNGIE), primary coenzyme Q10 deficiency, and Leigh syndrome caused by LRPPRC variants." (PMID 41480351, 2025). "Phenotypes resembling MNGIE may be seen in patients with other mitochondrial DNA depletion syndromes including POLG or RRM2B mutations and Kearns-Sayre syndrome." (PMID 30627136, 2018). "Induced pluripotent stem cell (iPSC)-derived neurons from patients with DNA polymerase gamma, catalytic subunit (POLG)-related mitochondrial DNA depletion syndrome exhibit decreased mitochondrial content and ATP." (PMID 40161853, 2025). "For example, about 2 percent of the general population are carriers of the POLG gene located at 15q26.1 band and leads to mitochondrial DNA depletion syndrome and related disorders." (PMID 36674736, 2023). "Mitochondrial DNA depletion syndromes (MDS) are often caused by defective proteins involved in the mtDNA replication machinery, such as POLG, or in dNTP metabolism, such as p53R2." (PMID 34830106, 2021). "Using exome sequencing, this patient was diagnosed with a rare Polymerase Gamma (POLG)-related mitochondrial DNA (mtDNA) depletion syndrome." (PMID 34194468, 2021). "To date, mutations in just four of these genes – POLG, PEO1, RRM2B and recently TK2 – have been described as causes of both infantile mtDNA depletion syndromes and adult-onset, multiple mtDNA deletion disorders." (PMID 22508010, 2012). "Three of the detected genes, POLG, NPC1, and CFTR, were not included in the old 18-gene panel and patients harboring variants in them were molecular diagnosed with mitochondrial DNA depletion syndrome, NPC and CF, respectively." (PMID 37168916, 2022).
Encephalopathy (11 papers, 2013 to 2026). Encephalopathy is a term that means brain disease, damage, or malfunction. "In this research, a 3D brain organoid model is developed to study POLG‐related encephalopathy, a mitochondrial disease stemming from POLG mutations." (PMID 38445970, 2024). "POLG-associated encephalopathy has been postulated to give rise to a distinct phenotype, including variable age at onset, either recessive or dominant inheritance pattern and peculiar neuroimaging findings characterized by predominant posterior ischemic lesions and lack of cerebral calcification." (PMID 23324391, 2013). "Mutations in POLG and DGUOK have been previously implicated in mitochondrial disorders with common phenotype such as mitochondrial respiratory complex defect, mitochondrial DNA depletion and encephalopathy." (PMID 33484326, 2021). "For example, the downregulation of NEFL, MAP1B, and GAP43—genes essential for axonal stability, cytoskeletal organization, and synaptic plasticity—may underlie the progressive cognitive decline and neurodevelopmental delay frequently reported in POLG‐related encephalopathies." (PMID 41355579, 2026).
mitochondrial recessive ataxia syndrome (11 papers, 2006 to 2025). "By contrast, ATXN8/OS-related SCA8 and mitochondrial recessive ataxia syndrome (MIRAS) resulting from mutations in POLG have been reported in Finland." (PMID 34600502, 2021). "Mitochondrial recessive ataxia syndrome (MIRAS) is caused by mutations in the polymerase γ (POLG) gene, considered to be the replicative polymerase for mitochondrial DNA." (PMID 17112370, 2006). "The frequency of mitochondrial DNA polymerase gamma (POLG) mutations, which lead to mitochondrial recessive ataxia syndrome (MIRAS), is also relatively high, Moreover, although Fragile X–Associated Tremor/Ataxia Syndrome (FXTAS) has been reported in Finland, no epidemiological data are available." (PMID 37373667, 2023).
optic atrophy (11 papers, 2017 to 2025). A disorder characterized by loss of optic nerve fibers. "Another case study, reports two patients with a MNGIE-like phenotype exhibiting optic atrophy associated with a novel POLG mutation affecting the C- terminal sub-domain of the protein." (PMID 30627136, 2018). "In addition, Kearns-Sayre syndrome, Leigh syndrome, MERRF, LHON (Leber’s hereditary optic neuropathy), and non-syndromic mitochondrial diseases, especially POLG mutations, have also been associated with similar clinical pictures." (PMID 41438888, 2025). "Nevertheless, rare cases of optic atrophy have been attributed to POLG mutations." (PMID 31550237, 2020). "Moreover, variants in nuclear genes OPA1, OPA3, TYMP and POLG have been reported in patients with other optic atrophies with phenotypes that could be similar to LHON." (PMID 36827238, 2023). "The reported yield of nuclear and mitochondrial DNA sequencing in bilateral optic atrophy is around 20% and includes pathogenic variants in the OPA1, mtDNA genes, or rarely WFS1, MFN2, POLG, ACO2, and DNAJC30 genes." (PMID 36294366, 2022).
Alpers-Huttenlocher syndrome (10 papers, 2011 to 2025). "Advances in genetic testing, including whole-exome and whole-genome sequencing, now allow for early and accurate identification of pathogenic variants such as MT-ND gene mutations in Leigh syndrome and POLG mutations in Alpers-Huttenlocher syndrome." (PMID 40728973, 2025). "Recessive POLG mutations have been described in Alpers-Huttenlocher syndrome associated with mtDNA depletion." (PMID 28324239, 2017). "Finally, the mtDNA damage caused by POLG mutations in Alpers-Huttenlocher syndrome, SANDO, and SCAE syndrome is unclear." (PMID 28324239, 2017). "Genetic analysis revealed a homozygous mutation in the DNA Polymerase Gamma, Catalytic Subunit (POLG) gene (c.1399G>A; p.Ala467Thr), confirming a diagnosis of Alpers-Huttenlocher syndrome." (PMID 39958089, 2025). "Similarly, Alpers-Huttenlocher Syndrome (AHS) though primarily rooted in defective mtDNA replication due to POLG mutations, ultimately disrupts OXPHOS by impairing the synthesis of ETC components encoded in mtDNA." (PMID 40728973, 2025).